PCMT1 (protein-L-isoaspartate (D-aspartate) O-methyltransferase)
Diseases named in the same sentence as PCMT1 in open-access papers (continued):
Sharing a sentence is not in itself a finding about the gene and the disease.
liver cancer (3 papers, 2022 to 2025). An epithelial or non-epithelial malignant neoplasm that arises from the liver. "It is noteworthy that higher expression of PCMT1 in liver cancer patients is associated with poorer OS and PFS." (PMID 37596654, 2023). "Despite investigations into PCMT1's role in various tumors, its significance in liver cancer remains elusive." (PMID 37596654, 2023). "Our study highlights the potential of PCMT1 as a prognostic biomarker and therapeutic target in liver cancer." (PMID 37596654, 2023). "In order to further investigate the role of PCMT1 in liver cancer, we first analyzed the expression of PCMT1 in tumor tissue and adjacent tissue of liver cancer patients." (PMID 37596654, 2023). "Then, we established a stable cell line with low expression of PCMT1 through shRNA, in order to further study the role of PCMT1 in liver cancer cell lines." (PMID 37596654, 2023). "To explore the possible mechanisms of PCMT1 in liver cancer progression, we conducted RNA transcriptome sequencing and analyzed the differentially expressed genes between the two groups with or without PCMT1 knockdown." (PMID 37596654, 2023). "We employed RNA transcriptome sequencing to explore the potential mechanism of PCMT1's role in liver cancer." (PMID 37596654, 2023). "We validated the expression of apoptosis-related proteins, BAX and BCL-2, following PCMT1 knockdown in two liver cancer cell lines." (PMID 37596654, 2023). "The results showed that PCMT1 expression was significantly higher in liver cancer tissue than in adjacent tissue." (PMID 37596654, 2023). "Based on our analysis, PCMT1 is likely to impact the proliferation of liver cancer cells as well as the formation of the tumor microenvironment." (PMID 37596654, 2023). "Through gene expression profiling analysis and in vitro and in vivo experiments, we further explored the potential mechanisms of PCMT1 in the progression of liver cancer." (PMID 37596654, 2023). "For instance, PCMT1 knockdown in liver cancer cells could promote their apoptosis while also limiting their proliferation and survival." (PMID 39235556, 2025). "Our findings suggest that PCMT1 acts as a promoter of liver cancer progression and may serve as a novel prognostic indicator and therapeutic target for patients with LIHC." (PMID 37596654, 2023). "Lastly, we examined EMT-related proteins and found that PCMT1 knockdown could decrease EMT in liver cancer cells." (PMID 37596654, 2023). "Therefore, we utilized publicly available databases and integrated bioinformatics methods to conduct a preliminary investigation into the relationship between PCMT1 expression and liver cancer patient prognosis." (PMID 37596654, 2023). "Further research is needed to elucidate the precise molecular mechanisms by which PCMT1 affects liver cancer progression and its impact on the immune microenvironment, paving the way for the development of novel therapeutic approaches for liver cancer patients." (PMID 37596654, 2023). "Through CCK8 and Transwell experiments, we found that knocking down PCMT1 could significantly inhibit the growth and migration of liver cancer cells." (PMID 37596654, 2023). "Therefore, our results suggest that PCMT1 may be a crucial molecule in liver cancer progression." (PMID 37596654, 2023). "Our research findings indicate a close correlation between PCMT1 expression and clinical features as well as prognosis of LIHC patients, highlighting its potential as a therapeutic target and prognostic assessment in liver cancer." (PMID 37596654, 2023). "Initially, we conducted Western blotting to examine the protein expression levels of PCMT1 in the tumor tissue and adjacent non-tumor tissue of liver cancer patients." (PMID 37596654, 2023).
lung adenocarcinoma (3 papers, 2021 to 2022). A carcinoma that arises from the lung and is characterized by the presence of malignant glandular epithelial cells. "In our study, we first performed a pancancer analysis of PCMT1, and the results showed that PCMT1 is highly expressed in a variety of cancers, including confirmed lung adenocarcinoma." (PMID 35535040, 2022). "It is reported that PCMT1 is a predictive biomarker for poor prognosis in surgically resected lung adenocarcinoma." (PMID 33898446, 2021). "In lung adenocarcinoma, previous studies found that the expression of PCMT1 was significantly higher in patients with clinically advanced or invasive adenocarcinoma than in patients with clinically early or preinvasive adenocarcinoma." (PMID 33898446, 2021).
Parkinson’s (3 papers, 2014 to 2023). "Some studies have reported that PCMT1 is closely related to the occurrence of several neurological diseases, including Alzheimer’s disease, Parkinson’s disease, and multiple sclerosis." (PMID 37899170, 2023). "Genes showing similar co-expression patterns have been previously linked to Alzheimer’s (ANK1) and Parkinson’s disease (UBE2E2, PCMT1, HPRT1 and RIT2)." (PMID 25493648, 2014).
cervical cancer (2 papers, 2022 to 2025). A primary or metastatic malignant neoplasm involving the cervix. "In addition, overexpression of the PCMT1 was correlated with worse prognosis in cervical cancer." (PMID 39235556, 2025).
lymph node metastasis (2 papers, 2023 to 2025). "Our studies confirmed that PCMT1 was overexpressed in PCa cells and tissues, and we found PCMT1 expression was closely associated with Gleason score, clinical stage, lymph node metastasis, and bone metastasis of patients with PCa." (PMID 37899170, 2023). "Univariate Cox regression analysis showed that expression of PCMT1, age, stage, lymph-node metastasis, distant metastasis, and recurrence were statistically significant prognostic factors of patients overall survival." (PMID 39235556, 2025).
ovarian carcinoma (2 papers, 2022 to 2023). A malignant neoplasm originating from the surface ovarian epithelium. "In line with that, our data demonstrated that knockout of PCMT1 in the anoikis-resistant SKOV3 ovarian carcinoma cell line caused significant apoptosis in response to detachment from the ECM." (PMID 35033172, 2022). "Among the genes identified, protein-L-isoaspartate (D-aspartate) O-methyltransferase (PCMT1) was found to be the most highly associated with anoikis resistance in ovarian cancer." (PMID 35033172, 2022). "Strikingly, treatment with an antibody against extracellular PCMT1 effectively reduced ovarian cancer cell invasion and adhesion." (PMID 35033172, 2022). "Further, its invasion potential can be inhibited by a PCMT1 blocking antibody, and patient data sets point to a positive correlation between PCMT1 expression and ovarian cancer metastasis." (PMID 35033172, 2022). "To further investigate the function of PCMT1 in ovarian cancer, we transfected the PCMT1-KO cells with either empty vector (control) or PCMT1-HA for a rescue experiment." (PMID 35033172, 2022). "Taken together, our CRISPR screen, clinical specimen analysis, and PCMT1 knockdown/knockout validation identified that PCMT1 was essential to anoikis resistance in ovarian cancer." (PMID 35033172, 2022). "To gain insight into the mechanism by which PCMT1 promotes cell metastasis traits in ovarian cancer, we performed IP-MS." (PMID 35033172, 2022). "PCMT1 profiling in human ovarian cancer specimens revealed significantly increased PCMT1 expression in metastases compared with primary tumors." (PMID 35033172, 2022). "We also found that the expression of PCMT1 was associated with the serum expression of CA125, which is the biomarker of progression in ovarian cancer." (PMID 35033172, 2022). "Taken together, our experiments demonstrated that PCMT1 knockout inhibited metastasis-relevant traits of ovarian cancer cells in vitro and that re-expression of PCMT1 in PCMT1-KO cells rescued the phenotype." (PMID 35033172, 2022). "To determine the significance of PCMT1 in epithelial ovarian cancer (EOC) progression, we compared the expression of PCMT1 in 72 primary tumor tissues and 26 metastatic tumor tissues by IHC analysis." (PMID 35033172, 2022). "Taken together, our experiments demonstrated that PCMT1 expression is essential for maintaining the metastatic traits of ovarian cancer cells in vitro." (PMID 35033172, 2022). "Our data indicated that PCMT1 expression was positively related to the clinical stage of ovarian cancer (P = 0.0386) and metastatic tumor size (P = 0.0466), whereas it was not correlated with patient age (P = 0.7175), primary tumor size (P = 0.7677), or tumor histology type (P = 0.3455)." (PMID 35033172, 2022). "Since we have demonstrated that PCMT1 is involved in anoikis resistance, we asked whether it could also affect cell migration, adhesion and invasion in ovarian cancer cells." (PMID 35033172, 2022). "We wanted to explore the role of PCMT1 secreted into the ECM in ovarian cancer." (PMID 35033172, 2022). "Interestingly, PCMT1 was released from ovarian cancer cells, and interacted with the ECM protein LAMB3, which binds to integrin and activates FAK-Src signaling to promote cancer progression." (PMID 35033172, 2022). "Importantly, in vitro intervention with an antibody targeting PCMT1 almost abolished the effect of secreted PCMT1, illustrating a potential medical application for ovarian cancer metastasis intervention." (PMID 35033172, 2022). "Hence, for comprehensive study the role of PCMT1 in ovarian cancer progression, large cohort of patient samples with different histological type of ovarian cancer was needed." (PMID 35033172, 2022).
ovarian carcinoma (continued). "In this study, we evaluated the clinical relevance of PCMT1 levels with ovarian cancer progression in patient samples and dissected the mechanism of how extracellular PCMT1 contributes to cancer progression through modulation of LAMB3, which may be used as a serum marker for monitoring metastasis." (PMID 35033172, 2022). "Moreover, PCMT1 is secreted from cancer cells to the extracellular space, suggesting that serum PCMT1 levels may serve as a promising marker of the metastatic propensity of ovarian cancer." (PMID 35033172, 2022). "It is interesting to note that when ovarian cancer cells are detached from the ECM, upregulation of both PCMT1 and LAMB3 and spheroid formation are observed." (PMID 35033172, 2022).
prostate carcinoma (2 papers, 2023 to 2026). A carcinoma that arises from epithelial cells of the prostate gland. "Clinically, USP13 was significantly up-regulated in prostate cancer tissues and positively associated with PCMT1 expression." (PMID 42056074, 2026). "Our studies demonstrate that inhibition of USP13 can offer a viable therapeutic option to overcome enzalutamide resistance in prostate cancer patients with USP13/PCMT1-overexpression." (PMID 42056074, 2026). "However, there are few reports on the role of PCMT1 in prostate cancer (PCa)." (PMID 37899170, 2023).
sarcoma (2 papers, 2017 to 2022). A usually aggressive malignant neoplasm of the soft tissue or bone. "PCMT1 was verified using the Western blot analysis to cross-react with the antisera of A5, and a protein antigen of A5 with significant immunotherapeutic effects on S180 sarcoma was successfully created by the induction of antibodies targeting for PCMT1." (PMID 29212247, 2017).
stomach adenocarcinoma (2 papers, 2022 to 2023). "There are no studies on EWSR1 and PCMT1 to confirm that they are related to the occurrence or prognosis of stomach adenocarcinoma, which can be used as points for further research." (PMID 35686089, 2022).
triple-negative breast carcinoma (2 papers, 2023 to 2025). An invasive breast carcinoma which is negative for expression of estrogen receptor (ER), progesterone receptor (PR), and human epidermal growth factor receptor 2 (HER2). "The overexpression of the PCMT1 protein in triple negative breast cancer significantly correlated with shorter overall survival." (PMID 39235556, 2025). "PCMT1 expression was a prognostic in the TCGA TNBC cohort, high expression predicts shorter overall survival in triple-negative breast cancer." (PMID 39235556, 2025).
adrenocortical carcinoma (1 paper, 2022). "The results of immune correlation evaluation showed that in addition to adrenocortical carcinoma (ACC), lymphoid neoplasm diffuse large B cell lymphoma (DLBC), and uveal melanoma (UVM), PCMT1 has varying degrees of correlation with the immune infiltrating cells of a variety of human cancers." (PMID 35535040, 2022).
breast ductal carcinoma (1 paper, 2022). "The heat map shows that PCMT1 is highly expressed in human breast ductal carcinoma cell lines, such as HCC1500, HCC1419, and EFM19 cell lines, while the expression is lowest in the HCC202 cell line (human breast primary ductal carcinoma cells)." (PMID 35535040, 2022).
COVID-19 (1 paper, 2024). A disease caused by infection with severe acute respiratory syndrome coronavirus 2. "PCMT1 was negatively correlated with INR in COVID-19 patients but not linked to thrombosis in the literature." (PMID 38760690, 2024). "Our COVID-19 patients had decreased expression of PCMT1, a carboxyl methyltransferase." (PMID 38760690, 2024). "SerpinB5, ERRa, and IGFBP-5 measurements in COVID-19 patients were mainly lower than healthy controls and exhibited a positive correlation with PTT; however, similar to PCMT1, none of the correlated proteins have been linked to thrombosis previously." (PMID 38760690, 2024).
glioblastoma (1 paper, 2022). The most malignant astrocytic tumor (WHO grade IV). "In addition, the latest research shows that PCMT1 promotes the migration and invasion of human U-87 MG and U-251 MG glioblastoma cell lines and plays a key role in the growth of glioblastoma." (PMID 35535040, 2022).
leukemia (1 paper, 2022). A malignant (clonal) hematologic disorder, involving hematopoietic stem cells and characterized by the presence of primitive or atypical myeloid or lymphoid cells in the bone marrow and the blood. "Conversely, downregulation of PCMT1 increases apoptosis upon DNA damage in leukemia." (PMID 35033172, 2022).
lymphoma (1 paper, 2022). A malignant (clonal) proliferation of B- lymphocytes or T- lymphocytes which involves the lymph nodes, bone marrow and/or extranodal sites. "The down-regulated CAPZA1, CAPZB, EFHD2, EZR and PCMT1 proteins are involved in cell–cell adhesion; their reduced levels are compatible with the metastatic behavior of lymphoma cells." (PMID 36291816, 2022).
metastatic cancer (1 paper, 2022). A carcinoma which has spread from the original site of growth to another anatomic site. "Quantitative real-time PCR (qRT-PCR) and immune-histochemistry (IHC) were used to measure differentially expressed PCMT1 in primary tissues and metastatic cancer tissues." (PMID 35033172, 2022).
metastatic tumor (1 paper, 2022). "The results showed that compared with that in the corresponding primary serous ovarian cancer, the mRNA level of PCMT1 was increased in metastatic tumor tissue for 10 pairs of patients." (PMID 35033172, 2022). "Importantly, PCMT1 was highly expressed in late-stage metastatic tumors compared to early-stage primary tumors." (PMID 35033172, 2022). "By carrying out quantitative real-time PCR (qRT-PCR), we found that, compared with those in the corresponding primary serous ovarian cancer, the mRNA levels of KCTD10, PCMT1, and ACTR10 were significantly increased in metastatic tumor tissues." (PMID 35033172, 2022).
nasopharyngeal carcinoma (1 paper, 2025). A carcinoma arising from the nasopharyngeal epithelium. "CircCLASP2 increases the translation of protein-L-isoaspartate (D-aspartate) O-methyltransferase (PCMT1) through binding to nuclear DNA Helicase 9 (DHX9), which results in nasopharyngeal carcinoma (NPC) progression." (PMID 40710359, 2025).
neuroblastoma (1 paper, 2022). Neuroblastoma (NB) is the most common solid, extracranial childhood tumor. "In dopamine-induced neuroblastoma cell death, PCMT1 protects cells from apoptosis by affecting ROS levels and caspase-3/9 activity." (PMID 35033172, 2022).
prostate tumor (1 paper, 2026). "Notably, inhibition of USP13 significantly decreases prostate tumor growth and improves enzalutamide treatments through PCMT1 suppression." (PMID 42056074, 2026).
rheumatoid arthritis (1 paper, 2023). A chronic, systemic autoimmune disorder characterized by inflammation in the synovial membranes and articular surfaces. "Another study constructing a genetic network for rheumatoid arthritis by evaluating genome-wide SNPs showed that PCMT1 is within the 41 identified significant SNPs, which is relevant to rheumatoid arthritis." (PMID 37759792, 2023).
serous ovarian cancer (1 paper, 2022). "However, in this study, we mainly examined the expression of PCMT1 in serous ovarian cancer with limited number." (PMID 35033172, 2022).
subarachnoid hemorrhage (1 paper, 2023). A serious neurological disorder characterized by intracranial hemorrhage into the subarachnoid space. "Furthermore, after subarachnoid hemorrhage, MST1 is activated and promotes neuronal apoptosis, which can be significantly inhibited by PCMT1." (PMID 37596654, 2023).
uterine carcinoma (1 paper, 2022). A carcinoma involving a uterus. "The results show that there is a significant positive correlation between PCMT1 expression and tumor mutation burden in multiple tumor types, including ACC, uterine carcinoma (UCS), and BRCA." (PMID 35535040, 2022).